CS (citrate synthase)
Diseases named in the same sentence as CS in open-access papers (continued):
Sharing a sentence is not in itself a finding about the gene and the disease.
pancreatic cancer (5 papers, 2014 to 2024). "Obviously, increasing of both availability of intracellular citrate and CS enzyme activity are directly associated and have been reported in pancreatic cancer." (PMID 38425123, 2024). "Here we have reported that CS silencing resulted to be synergetic with gemcitabine treatment in pancreatic cancer cell lines." (PMID 38425123, 2024). "Excessive Citrate Synthase (CS) activity has previously been observed in pancreatic tumor tissue when compared to adjacent non‐neoplastic tissue to feed tumor with citrate." (PMID 38425123, 2024). "Enhanced citrate synthase activity in pancreatic cancer can promote the conversion of glucose to lipids, thereby maintaining pancreatic cancer’s metabolism." (PMID 37087461, 2023). "Other reports have determined that the activity of citrate synthase was increased in pancreatic cancer cells in comparison to adjacent normal tissue." (PMID 25923219, 2015). "It is likely that enhanced citrate synthase activity contributes to the conversion of glucose to lipids in pancreatic cancer providing substrate for membrane lipids synthesis." (PMID 25545012, 2014). "Citrate Synthase is a key enzyme in pancreatic cancer metabolism." (PMID 38425123, 2024). "In this study, we present evidence demonstrating that the knockdown of CS in Mia‐Paca 2 and CRL‐2558 cell lines results in increased sensitivity to gemcitabine, a commonly used chemotherapy drug for pancreatic cancer." (PMID 38425123, 2024).
glioblastoma (4 papers, 2010 to 2024). The most malignant astrocytic tumor (WHO grade IV). "Of particular interest was the specific expression of ATP6v0A1, STRADA, PCNP and CS transcript variants, analyzed in patients affected by glioblastoma, which confirmed all the predicted cassette exons, thus demonstrating the reliability of our computational analysis." (PMID 20813049, 2010). "The CoQ10 levels expressed as a ratio to citrate synthase (CS) activity were reduced in glioblastoma cultures relative to the control (see UP-029 (p < 0.005), SEBTA-023 (p < 0.005), and UP-007 (p < 0.00005))." (PMID 31323957, 2019). "Of note, our data are confirmed by independent studies showing lower activity of HK, SDH and ACSS2 and higher activity of CS in LGG compared to glioblastoma." (PMID 28467784, 2017). "The validation of the cassette exons specific for the nervous system, detected for ATP6v0A1, STRADA, PCNP and CS genes, prompted us to analyze their expression in patients affected by glioblastoma, the most frequent form of primary intracranial malignancy." (PMID 20813049, 2010).
glioma (4 papers, 2013 to 2024). A benign or malignant brain and spinal cord tumor that arises from glial cells (astrocytes, oligodendrocytes, ependymal cells). "We first determined the levels of CcO and CS activity in mitochondria isolated from 58 primary glioma tissues (training samples, Birmingham cohort) and 12 tissue samples from normal brain (epilepsy patients)." (PMID 23593382, 2013). "By analyzing The Cancer Genome Atlas (TCGA) data, we found that OGDH mRNA levels were significantly downregulated in IDH-mutated gliomas compared with other TCA cycle enzymes, including citrate synthase (CS), succinate dehydrogenase complex subunit B (SDHB), and fumarate hydratase (FH)." (PMID 39872214, 2024). "CS and aconitase (ACO1/2), enzymes that function upstream of citrate oxidation, were expressed at higher levels in IDH1MUT glioma than in IDH1WT glioma." (PMID 28467784, 2017).
hepatocellular carcinoma (4 papers, 2016 to 2025). A malignant tumor that arises from hepatocytes. "Therefore, we utilized CS K375E and K375R mutants to simulate succinylation and desuccinylation of CS, respectively, to further investigate the mechanism by which CS succinylation affects the progression of hepatocellular carcinoma." (PMID 40557149, 2025).
Hyperglycemia (4 papers, 2018 to 2024). An increased concentration of glucose in the blood. "These treatments abolished the biphasic hyperglycemia-induced response in citrate synthase activity, and the desipramine-treated group displayed a time profile closely corresponding to that of the control group (p > 0.05, n = 5)." (PMID 32481596, 2020). "On the contrary, berberine supplementation reverts mitochondrial dysfunction induced by high fat diet and hyperglycemia in skeletal muscle in rat in part by increasing citrate synthase activity." (PMID 30006630, 2018). "In this study, we observed no significant changes in mitochondrial citrate synthase activity in hyperglycemia in the absence or presence of polyphenols." (PMID 39309231, 2024). "In addition, we did not observe meaningful changes of citrate synthase activity under the influence of hyperglycemia, both in control and WWOX KO cells." (PMID 35328751, 2022).
cognitive decline (3 papers, 2021 to 2022). "Of note, citrate synthase expression levels have been associated to cognitive decline in aged animals." (PMID 35228511, 2022).
colorectal cancer (3 papers, 2021 to 2025). A primary or metastatic malignant neoplasm that affects the colon or rectum. "Even though we did not see significant changes in CS mRNA expression between normal mucosa and tumor tissues, the TCGA data demonstrate a significant correlation between the expression of CS and FASN in human colorectal cancer." (PMID 35742953, 2022).
metabolic syndrome (3 papers, 2013 to 2022). A cluster of metabolic risk factors for CARDIOVASCULAR DISEASES and TYPE 2 DIABETES MELLITUS. "Moreover, it has been recently shown that simvastatin attenuates increases in cardiorespiratory fitness and skeletal muscle mitochondrial content (citrate synthase enzyme activity) when combined with exercise training in overweight or obese patients at risk of the metabolic syndrome." (PMID 24023786, 2013). "Some of the DE proteins predicted to affect mitochondrial function also cause dyslipidemia, including MECR, CS, ACLY, AOX3, and COX6B1 by RIS, and CYCS, COX6B1, and ENO3 by OLAN." (PMID 33302598, 2020). "In obese/metabolic syndrome patients treated with simvastatin, a reduced response to aerobic exercise training was noted with a lower increment in oxygen uptake and 4.2% reduction in citrate synthase activity." (PMID 35628225, 2022).
osteosarcoma (3 papers, 2018 to 2022). A usually aggressive malignant bone-forming mesenchymal neoplasm, predominantly affecting adolescents and young adults. "The value of CS gene in evaluating the immunotherapy response and clinical outcome of osteosarcoma (OS) has not been reported, and an accurate risk model based on CS gene has not been developed for OS patients." (PMID 36106335, 2022).
Rickettsia infection (3 papers, 2021 to 2025). "Rickettsia infection in Haemaphysalis hystricis ticks infesting dogs was first screened in Taiwan by nested-PCR assay targeting the citrate synthase gene (gltA) of Rickettsia." (PMID 40005788, 2025). "sanguineus ticks collected from 158 dogs of four districts of Tainan city were examined for Rickettsia infection by nested-PCR assay targeting the citrate synthase (gltA) and outer membrane protein B (ompB) genes of Rickettsia." (PMID 36367866, 2022).
sarcopenia (3 papers, 2019 to 2026). Progressive decline in muscle mass due to aging which results in decreased functional capacity of muscles. "Since diminished mitochondria function is also a hallmark of sarcopenia, mitochondrial respirometry and citrate synthase levels were measured from quadriceps muscles of WT and Z-PBS mice." (PMID 37535205, 2024).
systemic lupus erythematosus (3 papers, 2024 to 2025). An autoimmune multi-organ disease typically associated with vasculopathy and autoantibody production. "We have previously identified two important nAAbs recognizing a mitochondrial inner membrane enzyme, citrate synthase (CS) and topoisomerase I, a major autoantibody target in systemic sclerosis (SSc) and systemic lupus erythematosus (SLE)." (PMID 38542402, 2024).
autoimmune disease (2 papers, 2019 to 2023). A disorder resulting from loss of function or tissue destruction of an organ or multiple organs, arising from humoral or cellular immune responses of the individual to their own tissue constituents. "In our previous studies, we detected anti-citrate synthase (CS) IgM antibodies in HCs and patients with autoimmune diseases." (PMID 31817576, 2019).
Autoimmunity (2 papers, 2024). The occurrence of an immune reaction against the organism's own cells or tissues. "While heat shock proteins are well-studied, the role of citrate synthase in aging and autoimmunity remains unclear." (PMID 39519235, 2024). "We have not found any studies on the effects of targeted therapies, including biologics, on the production of anti-CS or anti-TOPO-F4 nAAbs in RA, AS, or any other autoimmune-inflammatory rheumatic diseases." (PMID 38542402, 2024). "Natural autoantibodies, such as anti-CS, anti-TOPO-F4, and anti-Hsp, might play an important role in inflammation, autoimmunity, and atherosclerosis." (PMID 38542402, 2024).
Bartonella infection (2 papers, 2016 to 2024). "Molecular assays, such as PCR amplification of specific gene targets (e.g., the Bartonella citrate synthase gene, gltA, ribC) and 16S rRNA sequencing of PCR products, are the most reliable methods to detect Bartonella infection and can be used for blood or fresh tissue specimens." (PMID 39592252, 2024).
Cachexia (2 papers, 2017 to 2021). Severe weight loss, wasting of muscle, loss of appetite, and general debility related to a chronic disease. "To investigate this point, we verified the mitochondrial function-associated gene expression of Cox5a, and citrate synthase, directly related to oxidative metabolism in the muscle of cancer cachexia groups." (PMID 34943780, 2021). "In cancer-cachexia rats compared to non-cachexia controls, activity of citrate synthase (CS) did not significantly differ between cancer-cachexia rats and the controls animals in any study muscle." (PMID 29255650, 2017).
cardiac hypertrophy (2 papers, 2016 to 2018). "To assess if the observed mitochondrial remodeling in cardiac hypertrophy and failure reflected changes in the total mitochondrial volume mass, we evaluated the activity of citrate synthase (CS), a key enzyme in the Krebs cycle." (PMID 26764143, 2016). "We cannot completely rule out the development of adaptations in AGAT-/- hearts, although we did not observe changes in mitochondrial respiration or citrate synthase activity (a marker of mitochondrial volume), nor did we observe cardiac hypertrophy at a histological or molecular level." (PMID 29236952, 2018).
coronary artery disease (2 papers, 2020). "While our results confirm that mitochondrial content is maintained in CLI patients, we also show that the validity of citrate synthase, COXIV, and β-HAD cannot reliably be extrapolated for use in CLI patients or in patients with ischemic heart disease." (PMID 32121096, 2020). "Additionally, neither the mRNA nor the protein levels of CS, FAT/CD36, or LPL as well as FAS, SREBP-1c and GPAT1 changed significantly in subjects with multivessel coronary artery disease." (PMID 31979197, 2020).
desminopathies (2 papers, 2016 to 2022). "In the context of human desminopathies it is, however, noteworthy that another study reported a marked decrease in the levels of respiratory chain proteins as well as in citrate synthase activity in cardiac tissue of patients harboring heterozygous DES mutations." (PMID 36233322, 2022). "In a recent study, the analysis of citrate synthase-normalized respiratory chain enzyme activities in skeletal muscle homogenates of a heterozygous R350P desminopathy patient, who was not related to both R350P desmin patients included in this study, gave normal results." (PMID 27393313, 2016).
endometrial cancer (2 papers, 2012 to 2015). Primary or metastatic malignant neoplasm involving the endometrium (mucous membrane that lines the endometrial cavity). "An increase in mtDNA content and citrate synthase (CS) activity, an enzyme marker of mitochondrial mass, has been reported in type I endometrial cancer compared to proliferative endometrial control tissues, suggesting an increase in mitochondrial biogenesis." (PMID 22676897, 2012). "The aim of this study has been to evaluate if mtDNA content and the citrate synthase (CS) activity, an enzyme marker of mitochondrial mass, increase in progression from control endometrium to hyperplasia to type I endometrial carcinoma." (PMID 22676897, 2012). "Interestingly, previous studies in human endometrial cancer have monitored i) mt-DNA content (by RT-PCR) and ii) mitochondrial mass (using the enzyme activity of citrate synthase), during the transition to malignancy." (PMID 26421711, 2015).
injury (2 papers, 2013 to 2024). Damage inflicted on the body as the direct or indirect result of an external force, with or without disruption of structural continuity. "Cortical citrate synthase activity is significantly decreased 7 days after traumatic brain injury." (PMID 24550822, 2013).
metastatic disease (2 papers, 2021). "For CS, SDH, and COX, metastatic tumors (Stage IV) showed approximately half (55.8–61.9%) the enzymatic levels of stage I tumors, although these differences were non-significant (p values > 0.05) due to high variation within each stage." (PMID 34078919, 2021).
migraine (2 papers, 2022 to 2023). "This is an intriguing finding which can also link the effect of PACAP to migraine as metabolic changes and mitochondrial dysfunction such as decreased activity of Complex I, III, IV and citrate synthase have been detected in migraine patients." (PMID 35216232, 2022). "Related studies evaluated the activity of platelet mitochondrial enzymes in patients with migraine with or without aura, and found that complex I, CS, and complex IV were damaged in migraine patients." (PMID 37123270, 2023).
mitochondrial DNA depletion syndrome (2 papers, 2016 to 2025). The mitochondrial DNA (mtDNA) depletion syndrome (MDS) is a clinically heterogeneous group of mitochondrial disorders characterized by a reduction of the mtDNA copy number in affected tissues without mutations or rearrangements in the mtDNA. "Increased citrate synthase activity suggests expanded mitochondrial mass but reduced effective OXPHOS (ratio of Complex IV to citrate synthase), echoing features of mtDNA depletion syndromes." (PMID 41480142, 2025).
myocardial infarction (2 papers, 2020 to 2021). Gross necrosis of the myocardium, as a result of interruption of the blood supply to the area, as in coronary thrombosis. "Previous studies have consistently reported that PD can reverse the broad myocardial infarction-induced decreases in the activities of mitochondrial oxidative metabolic enzymes, such as CS, and in the functioning of the ETC complexes." (PMID 33101591, 2020). "Moreover, citrate synthase activity has been shown to decrease after myocardial infarction and be partially regulated by MMP-9." (PMID 34517822, 2021).
Non-alcoholic fatty liver disease (2 papers, 2022 to 2026). "Reportedly, reduced citrate synthase activity has been shown to be associated with non-alcoholic fatty liver disease (NAFLD)." (PMID 36099304, 2022).
prostate carcinoma (2 papers, 2018 to 2022). A carcinoma that arises from epithelial cells of the prostate gland. "Most of the TCA enzymes are upregulated during the first metabolic shift in prostate cancer, and then either stay upregulated (CS, FH) or are downregulated (e.g. ACO2, OGDH, and SUCLG1) during the second shift." (PMID 29563510, 2018). "Though the ability of cells to secret citrate and spermine seems to be lost in metastatic samples, metastatic tissue from prostate cancer still contains traces of the CS gene profile compared to metastatic tissue originating from other organs (Hsu, dataset ID 19)." (PMID 35707723, 2022).
schizophrenia (2 papers, 2016 to 2024). A major psychotic disorder characterized by abnormalities in the perception or expression of reality. "Dysregulation of the Krebs cycle has also been implicated in schizophrenia as a result of differential abundance of several involved enzymes: such as aconitase 2 (ACO2), malate dehydrogenase 1 (MDH1), and citrate synthase (CS)." (PMID 26909022, 2016). "Schizophrenia showed an even ratio of upregulated to downregulated genes, with an approximately equal and small magnitude of expression change among genes; however, the rate-limiting enzyme CS was upregulated." (PMID 39125835, 2024). "In the TCA cycle, the genes CS, SDHA, and SUCLG2 were upregulated in schizophrenia but downregulated in ketosis, and SDHB was downregulated in both." (PMID 39125835, 2024).
viral infection (2 papers, 2022 to 2023). "Although the ATP production was enhanced after viral infection, K56 deacetylation of ACO2 suppressed BmN cellular ATP levels and mitochondrial membrane potential by affecting citrate synthase and isocitrate dehydrogenase activities compared with wild-type ACO2." (PMID 37896861, 2023).
vitamin D deficiency (2 papers, 2022 to 2023). A nutritional condition produced by a deficiency of VITAMIN D in the diet, insufficient production of vitamin D in the skin, inadequate absorption of vitamin D from the diet, or abnormal conversion of vitamin D to its bioactive metabolites. "Vitamin D deficiency was associated with increased oxidative stress and impaired mitochondrial function, as evaluated by decreased citrate synthase activity and PGC1a protein." (PMID 37892452, 2023). "Complex I, III, and IV had markedly reduced activities in plantaris muscle with vitamin D deficiency (−45%, p < 0.01; −31%, p < 0.05; −52%, p < 0.01, vs. control rats, respectively) whereas complex II and citrate synthase activities were unaffected." (PMID 36434267, 2022).
adenoma (1 paper, 2022). A neoplasm arising from the epithelium. "Immunohistochemistry staining of FASN and CS revealed that both are significantly upregulated in intestinal epithelium and adenomas in Apc/Cre mice as compared to intestinal tissues of wild-type C57BL/6J mice." (PMID 35742953, 2022). "We noted that even though the expression pattern of CS does not always recapitulate that of FASN, their expression seems to localize in the same areas of developing adenomas." (PMID 35742953, 2022).
amebiasis (1 paper, 2015). A parasitic infectious disorder caused by amoebas. "Since the pathway, consisting of two reactions catalyzed by serine acetyltransferase (SAT) and cysteine synthase (CS, O-acetylserine sulfhydrylase), does not exist in humans, it is a rational drug target against amebiasis." (PMID 26441896, 2015).
anaplasmosis (1 paper, 2021). "The 16S rRNA, citrate synthase, heat shock, and major surface proteins (Msp1, Msp2, Msp4, and Msp5) are the most targeted genes for the molecular diagnosis of anaplasmosis." (PMID 34941839, 2021).
asthma (1 paper, 2013). "To determine the effect of baicalein on mitochondrial function in the experimental asthma model, we measured cytochrome c oxidase activity and normalized by respective citrate synthase activity in lung mitochondria." (PMID 23646158, 2013).
astrocytomas (1 paper, 2022). "Taken together, we have demonstrated that lower CoQ10 levels and protein levels of COQ3, COQ5, COQ6, COQ7, COQ8A, and COQ9 were associated with higher tumor grades and lower CS activity or COX II level in human astrocytomas." (PMID 35204836, 2022). "In a previous study, we reported the alterations of primary antioxidant enzymes and decreased citrate synthase (CS) activities in different grades of human astrocytoma tissues." (PMID 35204836, 2022). "The increase of COQ4 level in Grade III astrocytomas compared with that in controls became significant after the level was normalized by either CS activity or COX II level." (PMID 35204836, 2022).